CD4 (CD4 molecule)
Diseases named in the same sentence as CD4 in open-access papers (continued):
Sharing a sentence is not in itself a finding about the gene and the disease.
acute GVHD (continued). "For example, ruxolitinib mitigates acute GVHD by reducing CXCR3 expression, which results in less T-cell infiltrates in target organs, and by decreasing IFN-γ and IL17A production in CD4+ T cells." (PMID 34305954, 2021). "Using this model, we recently reported that 1 × 106 to 2 × 106Itk‐deficient CD4+ and CD8+ T cells do not cause GVHD, compared to the same number of CD4+ or CD8+ T cells from WT mice which cause acute GVHD." (PMID 34919342, 2021). "But as well known, not only CD4+ and CD8+ T cells, but also M1/M2 monocytes and NK cells play an important role in the pathogenesis of acute GVHD, while the immune system dysregulation is different and complex by the type of acute GVHD." (PMID 34484183, 2021). "FRC network injury was consistently observed in several models of acute GVHD, although in contrast to a previous report we also observed FRC damage in a purely CD4+ T cell–dependent model, consistent with the upregulated expression of MHC class II on FRCs in the context of an inflammatory stimulus." (PMID 31917684, 2020). "Whereas recipients of BM only had no GVHD and all survived >80d mice receiving BM+CD4+ developed acute GVHD (median survival 12d, p<0.0001)." (PMID 23077665, 2012). "We hypothesized that defective intestinal colonization by CD4+ cells lacking TRPM7 kinase activity could affect acute GVHD." (PMID 29203869, 2017). "Similarly, acute GVHD had a negative impact on total CD4+ T-cell counts." (PMID 26098781, 2015). "We compared the effects of PMA stimulation alone on the CD3+CD4+, CD3+CD8+ and CD3− PBMC subsets for patients with and without previous acute GVHD before day +90 post-transplant." (PMID 35566660, 2022). "Early clinical studies linked higher γδ T cell counts to a higher incidence of acute GVHD, whether measured in the recipient or in the graft, but also reported decreased γδ T cell counts in patients with chronic GVHD, specifically the CD4 and CD8 double negative subset." (PMID 33680931, 2020). "In addition, CD4+ T cells, rather than CD8+ T cells, also depend on the migration of the CXCL12/CXCR4 axis to target organs in acute GVHD mice." (PMID 39840040, 2024). "A comparison of skin tissue biopsies from patients with acute GVHD vs those without revealed a significant increase in the proportion of CD70+ subgroups within CD8+ T cells, surpassing the increase observed in CD70+ subgroups within CD4+ T cells." (PMID 39840040, 2024). "Even though we did not perform a detailed study of IL-6 responsiveness in various CD4+/CD8+ T cell subsets, it seems justified to conclude that post-transplant circulating CD4+ and CD8+ T cells derived from patients with and without previous acute GVHD differ in their IL-6 responsiveness." (PMID 35566660, 2022). "Thus, early post-transplant CD3+CD4+ and CD3+ CD8+ T cell subsets differ in their IL-6 responsiveness; this responsiveness is modulated by antithymocyte globulin and differs between patients with and without previous acute GVHD." (PMID 35566660, 2022). "Thus, activated CD3+CD8+ T cells showed no major differences in IL-6 responsiveness when comparing patients with and without previous acute GVHD; this is in contrast to the CD3+CD4+ T cell subset that differed in STAT (Ser727) and mTOR (Ser2448) responses between the two patient subsets." (PMID 35566660, 2022).
food allergy (56 papers, 2010 to 2025). Gastrointestinal disturbances, skin eruptions, or shock due to allergic reactions to allergens in food. "It has been appreciated for many years that food allergy was associated with an allergen-specific type 2 cytokine profile, defined by production of IL-4, IL-5, and IL-13 from CD4+ T cells." (PMID 36880703, 2023). "This steady state CD4+ T cell response to food was disrupted by inflammatory challenge, and protection against food allergy in this context was associated with Treg clonal expansion and decreased proinflammatory gene expression." (PMID 37191720, 2023). "The spontaneous resolution of food allergy in children is associated with an increased frequency of peripheral blood CD4+ CD25+ Tregs after an OFC and a reduced proliferation of food allergen specific T cells." (PMID 29977438, 2018). "As altered mucosal CD4+ T cell responses are implicated in intestinal diseases of increasing prevalence, including food allergies and IBD, it is important to understand the factors that control effector and regulatory T cell homeostasis in the gut." (PMID 26910010, 2016). "In brief, we have discussed the eosinophil biology and its association to the food allergy, specifically the role of CD4+ T cells and iNKT cells, in the EGID pathogenesis." (PMID 27840774, 2015). "Recently, the suppressive capacity of CD4+CD25+CD127low/− Tregs in cord blood has been linked to the development of food allergy." (PMID 22272233, 2012). "However, if the primary exposure to a food protein occurs at the same time as the inflammatory stimulus, impaired Treg response and increased pro-inflammatory CD4+ T cell gene expression are observed in the gut, associated with the development of food allergy." (PMID 37191720, 2023). "Deletion of IL-4 under the Foxp3 promoter could eliminate susceptibility to food allergy, despite the fact that the mice still had conventional CD4+ type 2 T cells." (PMID 36880703, 2023). "If oral tolerance to a food protein was established prior to inflammatory challenge, then exposure to the same food protein during inflammatory challenge results in clonal expansion of gut Tregs associated with reduced proinflammatory CD4+ T cell gene expression and protection against food allergy." (PMID 37191720, 2023). "Allergen-specific CD4+ T cells play a pivotal role in the pathophysiology of food allergy and in the induction of tolerance during desensitization." (PMID 40574856, 2025). "Allergen-specific CD4+ T cells play a major role in the physiopathology of food allergy as well as in tolerance induction during desensitization." (PMID 40574856, 2025). "MLN serves as an important inductive site for CD4+ T cell activation in the pathogenesis of food allergies." (PMID 40509380, 2025). "Compared to allergen-tolerant infants, infants with food allergies have an overall increase in activated B cells, increased allergen-specific CD4+ T cells, and inflammatory monocytes." (PMID 41194920, 2025). "In cord blood, infants who developed food allergies showed a higher ratio of monocyte/CD4+ T cells, which would secrete higher amounts of inflammatory cytokines, such as IL-1β, IL-6, and TNF-α that further suppressed IL-2 expression by CD4+ T cells." (PMID 38263182, 2024). "The mechanism of a food allergy involves the stimulation of CD4+ T cells by food allergens, most often followed by differentiation into Th2 cells, making the Th2 cells dominate." (PMID 36673400, 2023). "To better understand the underlying immune mechanisms of the Th2-driven food allergy EoE, we first analyzed the systemic anti-OVA CD4 T-cell response." (PMID 36452260, 2022). "Nevertheless, IL-4 concentration, a key cytokine in the pathomechanism of food allergy, was significantly lower in the former group, confirming the protective effect of the transferred CD4+ T cells." (PMID 34207474, 2021). "This study clarified RARαplayed a crucial role in food allergy by promoting naive CD4(+) T cells to differentiate into Th2 cells." (PMID 34721398, 2021).
food allergy (continued). "During the development of food allergy, the activation of CD4+ T cells is usually affected by antigen present cells (APCs)." (PMID 34177885, 2021). "This study also reported an increased monocyte: CD4 T cell ratio in the cord blood of infants with food allergy." (PMID 33072108, 2020). "While conventional CD4+ Tregs have been extensively studied, the function of CD8+CD4– Tregs remains less characterized, but are thought to play an important role in preventing food allergy." (PMID 32292395, 2020). "Using integrated DNA methylation and transcriptomic profiling, we found that polyclonal activation of naive CD4+ T cells through the T cell receptor results in poorer lymphoproliferative responses in children with immunoglobulin E (IgE)-mediated food allergy." (PMID 30120223, 2018). "Here the authors study the epigenetic regulation of the naive CD4+ T cell activation response among children with IgE-mediated food allergy finding epigenetic dysregulation in the early stages of signal transduction through the T cell receptor complex." (PMID 30120223, 2018). "The initial stage of food allergy is the activation of T cells, pushing the differentiation of CD4+ T cells into Th2 cells in Payer's patches, mesenteric lymph nodes, and spleen." (PMID 28454097, 2017). "In this study, we examined the anti-allergic effects of baicalein in a mouse model of food allergy, on the differentiation of naïve CD4+ T cells to Treg cells via Foxp3 induction, and on intestinal barrier function via the regulation of TJs." (PMID 27561877, 2016). "Notably, LDHC gene (lactate dehydrogenase C) has been reported as hypomethylated in CD4+ T cells of children with food allergy." (PMID 41394805, 2025). "In the same line, the CCR9:DRD5 heteromer seems to be exclusively involved in the infiltration of CD4+ T-cells in the colonic mucosa upon inflammation, and not in homeostatic conditions, as Drd5−/− mice do not develop issues associated with food allergy." (PMID 39337509, 2024). "In a mouse model study, administration of baicalein at a dose of 20 mg kg−1 to mice with ovalbumin-induced food allergy alleviated the symptoms of food allergy and reduced the level of serum IgE and effector T cells by induction of CD4+Foxp3+T cell differentiation." (PMID 36902160, 2023). "Therefore, the skewing of naive CD4+ T cell differentiation into Th1 or Th2 effector cells, driven by the cytokine environment, is critical to the development of food allergy." (PMID 33571165, 2021). "Interestingly, a Th2-skewed environment, such as that type of food allergy, was favourable to the promotion of vitamin A metabolism and to the induction of a Foxp3+ RORγt+ phenotype on CD4+ T cells by the hydrolysates." (PMID 32245005, 2020). "Severe infiltration of CD4+ T cells and over production of the Th2 cytokines, including IL-4, IL-5 and IL-13 have been documented in the intestinal mucosa of humans and mouse models of GI food allergy." (PMID 31164117, 2019). "Furthermore, it was recently reported that baicalein effectively attenuated the symptoms of food allergy through its dual functions of the induction of CD4 + Foxp3 + T cells and enhancement of intestinal barrier function." (PMID 29143798, 2017). "Therefore, Bc-specific induction of CD4+Foxp3+ Tregs not only inhibits Th2 inflammation and anaphylaxis, but also suppresses Th17 pro-inflammatory responses in this mouse model of food allergy to ST." (PMID 28512288, 2017). "The role of Foxp3+/CD25+/CD4+ Tregs in development of food allergy is at present unclear." (PMID 22203855, 2012). "Future studies of CD4+ T cells in egg-allergic individuals will determine whether the IL-9 is being produced by Th9 or Th2 cells, and highlights the potentially central role of IL-9 in food allergy as indicated by studies in mouse models." (PMID 27788149, 2016).
food allergy (continued). "Another study relating to food allergy showed that EVs carry the allergen-MHC class 2 complexes and IL-10 and could induce Tr1 differentiation in healthy CD4+ T cells." (PMID 38674077, 2024). "Although, two out of the 10 papers on food allergies provided limited data showing that lipids can supress allergic sensitization to allergens when the lipids were delivered without the allergenic protein and by supressing CD3+CD4+ T cell populations." (PMID 35495627, 2022). "It is worth noting that the IL-4 in subjects with food allergies is primarily derived from CD4+ T cells rather than ILC2s, and IL-4 released by ILC2s has no discernible effect on food allergies." (PMID 34177881, 2021). "It will be important to characterize and validate Ara h 1, 3, and 6 dominant epitope by this CD154 epitope mapping approach given that a relatively high percentage of Ara h 1, 3, and 6-specific CD4 T cell express CCR6, which is potentially a producer of IL-17 as observed in other food allergy." (PMID 29988522, 2018). "Food allergy mice had a lower percentage of CD4+ CD25+ Foxp3+ T cells in the MLN compared to nonsensitized controls." (PMID 28250847, 2017). "The adoptive transfer of CD4+CD25+FoxP3+ Treg confined the protection mechanism and the depletion of CD25+ T cells resulted in pronounced disease exacerbation, thus confirming that Treg have an essential role in resolving food allergy in our model." (PMID 26517875, 2015). "Although the proportion of FoxP3+ cells among CD4 T cells did not vary, food allergies occurred more rapidly after liver grafting in patients who received basiliximab, raising questions as to Treg functionality in vivo in the absence of functional CD25." (PMID 20689592, 2010). "Previously, we found that naïve cord blood CD4+ T cells differentiated toward an IL-4-expressing phenotype when activated in the presence of TGF-β and monocyte-derived inflammatory cytokines, the latter are more highly secreted by infants who developed food allergy." (PMID 29922282, 2018).
leprosy (56 papers, 2011 to 2025). Leprosy is a chronic infectious disease affecting primarily the skin and peripheral nervous system. "Th17 population is another CD4+ Th subset, which is associated with inflammation that confirms the variance in leprosy." (PMID 37809252, 2023). "We identify expression of ACTR1A in CD4+ T cells as candidate effector of leprosy risk at this locus." (PMID 36121873, 2022). "In keeping with this, the leprosy association at 10q24.32 colocalises with determinants of gene expression in CD4+ T cells, skin and peripheral nerves." (PMID 36121873, 2022). "Our data are complementary to these observations, suggesting a model in which CD4+ T cell activation, determined at the level of the T cell as well as that of the antigen presenting cell, modifies susceptibility to leprosy." (PMID 36121873, 2022). "An eQTL operating in CD4+ T cells modifying leprosy risk reflects the established role of T cell-mediated immunity in leprosy biology." (PMID 36121873, 2022). "In CD4+ T cells the leprosy-associated locus is a determinant of ACTR1A expression, however in skin and peripheral nerves it determines TMEM180 expression." (PMID 36121873, 2022). "For decades the Th1-Th2 paradigm was associated with leprosy manifestations but more recently other CD4+ T cell populations as Th17 and T regulatory cells (Treg) have been implicated in the immunopathology of leprosy." (PMID 29883464, 2018). "It has been suggested that, among HIV-infected patients, the diagnosis of leprosy has been associated with patients’ immune improvement, characterized by elevated T-helper CD4+ lymphocyte counts and lower viral loads." (PMID 26029928, 2015). "Similarly, leprosy reversal reactions, characterised by painful inflammation of leprosy lesions, are associated with infiltration of IFNγ producing CD4+ T cells." (PMID 36121873, 2022). "To validate whether enhanced IL-6R expression on CD4+ T cells is causative of elevated IL-17A response in T1R leprosy patients, we studied the effect of blocking of IL-6R and IL-23R in MLSA induced IL-17A production by PBMCs cells in-vitro." (PMID 32934336, 2020). "Our and other studies had shown that CD4+FOXP3+T regulatory cells producing TGF-β were increased in stable lepromatous patients which may explain the anergy associated with this leprosy type." (PMID 27035913, 2016). "The adaptive immune response in leprosy, primarily regulated by T cells (including CD4+, CD8+, CD1-restricted, and γδ T cells), shapes disease presentation." (PMID 41306590, 2025). "The action of IL-10 in leprosy lesions leads to the differentiation of regulatory CD4+ T cells, as well as regulatory B cells that produce high levels of IL-10." (PMID 38381878, 2024). "There is an increased expression of PD-1 and PD-L1 on CD4+, B cells, and CD11c+ cells in leprosy patients." (PMID 37153623, 2023). "We assessed the expression of PD-1 on CD4+CD25+FoxP3+ Tregs derived from leprosy patients and healthy individuals to determine if it contributes to immune suppression." (PMID 37153623, 2023). "There is an increase of CD4+ T lymphocytes within the granuloma centers of leprosy patients with T1LR." (PMID 38130570, 2023). "The percentage of CD4+CD25+FoxP3+ Tregs was significantly higher in the PBMCs of lepromatous leprosy patients (12.53 ± 2.46%) compared with that in tuberculoid leprosy patients (7.15 ± 1.71%) and healthy individuals (4.42 ± 1.23%)." (PMID 37153623, 2023). "In the present study, we first evaluated the percentages of CD4+CD25+FoxP3+ Tregs in the PBMCs of leprosy patients as well as healthy controls." (PMID 37153623, 2023). "The spectrum of leprosy disease is defined by host T cell responses, with tuberculoid disease being characterised by robust CD4+ T cell IFNγ responses and patients with lepromatous disease failing to mount anti-M. leprae cell-mediated responses." (PMID 36121873, 2022). "Most studies on Treg in leprosy reactions focus on the CD4+ subset, and information concerning CD8+ cells still very scarce." (PMID 35924037, 2022).